BCL2 (BCL2 apoptosis regulator)
Diseases named in the same sentence as BCL2 in open-access papers (continued):
Sharing a sentence is not in itself a finding about the gene and the disease.
cancer (continued). "Previously, quercetin was found to promote ROS-stimulated apoptosis and autophagy in different cancers by activating caspase-3 and inhibiting anti-apoptotic proteins, such as Bcl-2 and Bcl-xl." (PMID 34025409, 2021). "Bcl-2 is induced by protein kinases and several signaling molecules which stimulate cancer development." (PMID 34638779, 2021). "Navitoclax exhibits significant single-agent efficacy against cancer cells with an overexpression of BCL-2 or BCL-XL proteins and yields synergistic effects with other drugs in various diseases." (PMID 34575429, 2021). "In the case of the prostate cell lines, an upregulation of the BCL2 gene was observed in the highest tested concertation, which was more pronounced in cancer cell lines." (PMID 34769400, 2021). "The novel series showed selective sub-micromolar IC50 growth-inhibitory activity against Bcl-2-expressing human cancer cell lines." (PMID 34830153, 2021). "Sustained pS70 of Bcl-2 in turn blocks oxidative stress-induced DNA damage to promote cancer cell survival." (PMID 34777681, 2021). "We examined the apoptosis by detecting annexin V-FITC/PI staining, the mitochondrial membrane potential (ΔΨm) disruption, reactive oxygen species (ROS) generation, the activity of caspase-3, and expression of the Bax and Bcl-2 in cancer cells." (PMID 35194432, 2021). "As supporting evidence, the fate of cancer cells is greatly influenced by the expression of Bcl-2; many cancer cells harboring overexpression of Bcl-2 exhibited resistance to conventional chemotherapies that trigger apoptosis." (PMID 33809701, 2021). "In the case of the anti-apoptotic protein Bcl-2, a significant decrease in the level of protein was observed after treatment with resveratrol in all of the tested cancer lines." (PMID 34770968, 2021). "has demonstrated anti-cancer activity and apoptosis of cancer cells and DNA fragmentation as well as induced activation of caspase-3, 8 and 9, down-regulation of Bcl-2, and up-regulation of Bax in human cervical cancer (Hela) and human chondrosarcoma cells." (PMID 34070936, 2021). "Inhibition of Bcl-2 for triggered pro-apoptotic signaling is considered a promising strategy for cancer treatment." (PMID 33535550, 2021). "TZB induces cellular apoptosis of cancer cells by inhibiting Bcl-2 and regulating the downstream pathways." (PMID 34669701, 2021). "Further, CSO can lead to cancer cell apoptosis through activating caspase-3, up-regulating Bax, and downregulating Bcl-2." (PMID 34829119, 2021). "Protein ubiquitination via the regulation of UPS plays a crucial role in anti-apoptotic protein degradation, including Bcl-2, Bcl-xL, and Mcl-1, resulting in the induction of cancer cell death." (PMID 34576269, 2021). "For example, butyrate (a product in the TCA cycle) is often elevated in cancer cells and has been shown to inhibit HDAC activity in colonocytes and cause the downregulation of some anti-apoptotic genes including Bcl-2." (PMID 34283054, 2021). "According to results of qRT-PCR, expression level of the Bcl-2 was reduced in the treated cancer cells." (PMID 33906308, 2021). "Reducing the proliferation of cancer cells is a way to control cancer cell amplification, and M. oleifera leaf extract significantly reduces the levels of c-myc, p-Bcl2, and Hsp70 to induce cell cycle stagnation." (PMID 34946594, 2021). "Anti-apoptotic Bcl-2 protein is one such protein that is overexpressed in many cancers, which makes it an ideal target for cancer therapy." (PMID 33926484, 2021).
cancer (continued). "Previous studies have shown that STAT3 activation subsequently increased c-myc, Bcl-2, and Mcl-1 transcription, thereby inducing cancer cell proliferation and survival." (PMID 33731185, 2021). "As a crucial survival mechanism, BCL-2 expression promotes tumourigenesis and therapy resistance by enabling cancer cells to evade apoptosis." (PMID 34073976, 2021). "In in vitro studies on BC, RXR ligands or retinoids are reported to induce apoptosis in BCL2-positive human cancer cells, and decreased vascularization in BC tumors in transgenic mice." (PMID 33478016, 2021). "Previously, we reported the identification of a novel BCL2 inhibitor, Disarib, which efficiently eradicated cancer cells with high BCL2 levels." (PMID 33976278, 2021). "A recent study reported the downregulation of miR-519a-3p in GBM and its role in enhancing chemosensitivity and promoting cancer cell autophagy via targeting the STAT3/B cell lymphoma 2 (Bcl2) signaling." (PMID 34867700, 2021). "Both Bax and Bcl-2 belong to the Bcl-2 family, and the ratio of Bax/Bcl-2 is relevant to the sensitivity or resistance of cancer cells to apoptotic stimuli and therapeutic drugs." (PMID 33520087, 2021). "Cell apoptosis has been regulated by the expression of the Bcl-2 and Bax proteins, Bcl-2 resists cell apoptosis and induces tumorigenesis, while the expression of Bax results in apoptosis of cancer cells." (PMID 35069196, 2021). "We also discussed a comprehensive study of Bcl-2 inhibitors as a therapeutic target for cancer therapy." (PMID 34638779, 2021). "Pimozide, another D2 blocking agent used for Tourette’s Disorder, can fight cancer cells, including the apoptotic effects in cancer cells and the decreased expression of Bcl-2." (PMID 34299028, 2021). "We further highlight the therapeutic activity of Bcl-2 inhibitors and their implications for the therapeutic management of cancer." (PMID 34638779, 2021). "Previous observation described that human cancer cells were sensitized to apoptosis induced by Bcl-2/Bcl-xL-targeting BH3 mimetics via hypoxia-mediated downregulation of Mcl-1." (PMID 34257274, 2021). "Administration of Res sensitizes cancer cells to apoptosis via NF-κB down-regulation leading to a decrease in the level of anti-apoptotic factor Bcl-2 and an increase in apoptotic factors caspase-3 and caspase-8." (PMID 33478512, 2021). "Treatment with melatonin enhances ER stress–mediated apoptosis in tunicamycin-treated cancer cells; this effect is associated with the down-regulation of COX-2 and Bcl-2 expressions and up-regulation of Bim, CHOP and Bax expressions." (PMID 33789681, 2021). "BCL2 gene codes for a mitochondrial anti-apoptotic protein, which can promote cell survival, including that of cancer cells, by inhibiting the apoptosis induced by oxidative stress." (PMID 34490245, 2021). "Inhibiting Survivin or Bcl-2 can improve chemosensitivity of cancer cells to paclitaxel and cisplatin." (PMID 33738259, 2021). "There is strong evidence that progesterone regulates bcl-2 expression in cancer and non-cancer cells." (PMID 34683909, 2021). "The inhibitor of the mPTP cyclosporin A inhibited, whereas Bcl-2 or Bcl-xL overexpression totally prevented edelfosine-induced apoptosis in cancer cells." (PMID 34065546, 2021). "Bax translocation to mitochondrial membrane in some cancer cells leads to a rise in the Bax/Bcl-2 proportion." (PMID 34711017, 2021). "YAP is a co-transcription factor that induces transcription of a variety of genes related to cell proliferation (E2F and Cyr61), cell survival (survivin and Bcl2), cancer stemness markers (Oct4, Nanog, and IGF-1R), and EMT markers." (PMID 34359714, 2021). "These are BH3 mimetics (they mimic the physiological activity of BCL-2 antagonists) and kill cancer cells by targeting their survival mechanisms." (PMID 33413657, 2021).
cancer (continued). "Instead, it is the high levels of BCL-2 protein expression that serves to predict poor prognosis, reduced overall and disease-free survival, and recurrence in cancers." (PMID 33799592, 2021). "A survey about the expression of Bcl-2 anti-apoptotic proteins in 68 human cancer cell lines showed that in many solid tumors, the expression level of Mcl-1 was much higher than that of other Bcl-2 anti-apoptotic members." (PMID 34746001, 2021). "This induced cancer cell death following cytokinesis failure results from the intrinsic caspases 3 and 9-mediated apoptotic pathway and is more efficient in cancer cell lines harbouring low level of the anti-apoptotic Bcl-2 and Mcl-1 proteins." (PMID 34294140, 2021). "The Bcl-2 family of apoptotic proteins is involved in cancer cell survival and proliferation, and combination of Bcl-2 inhibitor ABT-737 and mTOR inhibitor AZD8055 was highly synergistic in inducing caspase-dependent apoptosis in ARMS and ERMS cells." (PMID 35126101, 2021). "It is therefore vital that we understand how cancer cells modulate BCL2 expression to subvert apoptosis, in order to develop new treatments for this deadly disease." (PMID 33469000, 2021). "We found that known cancer driver genes were evenly distributed between proteins significantly interacting with BCL2 and other proteins in the G401 immunoprecipitate (i.e., the non-interactors)." (PMID 33972534, 2021). "It has been shown that TZB initiates the apoptosis signaling in cancer cells by suppressing the anti-apoptotic family, Bcl-2 members, which subsequently induces up-regulation of BAX, apoptosis inducer." (PMID 34669701, 2021). "The data showed that sumac at doses of 50 and 100 μM significantly inhibited the growth, proliferation, and viability of cancer cells by activating the apoptotic process via caspase-3 overexpression and the regulation of Bcl-2 anti-apoptotic protein." (PMID 33891003, 2021). "Ganoderma lucidum treatment upregulated the level of Bax and downregulated the level of Bcl-2, resulting in an increase in the ratio of Bax/Bcl-2 in cancer cells." (PMID 33906301, 2021). "Here, this review article highlights the present findings on the role of Bcl-2 in the progression of various cancers and its significance as a therapeutic target." (PMID 34638779, 2021). "Although the major focus around targeting BCL-2 proteins in cancer has been on the development of small molecule BH3-mimetics, there have also been some efforts towards the generation of BH3 peptide-based molecules." (PMID 34515749, 2021). "Q-PCR was used to reveal that the transcriptional levels of STAT3-supporting cancer cell-intrinsic hallmarks, including BCL2, MMP9, HIF-1α and PIM1, were all decreased with SPATS2 knockdown in both MHCC-97H and HCC-LM3 cell lines." (PMID 33391405, 2021). "Currently, small‐molecule inhibitors, that binds to pro‐survival BCL2 to actuate apoptosis of malignant cells, are applied in clinical therapy of cancer." (PMID 33838016, 2021). "Mechanistically, resveratrol has been shown to change the proteins of the BCL2 (B-cell lymphoma 2) family and activate pro-apoptotic proteins including BAK (BCL2 antagonist/killer) and BAX (BCL2 associated X), thus leading to cell death in cancer cells." (PMID 33802331, 2021). "Bcl2 is a major player in the cell death/cell survival pathway, and is known to be a key molecule in various cancers; thus, we investigated if Bcl2 was affected when treating OE33, OE19 and FLO-1 cells with resveratrol." (PMID 34830970, 2021). "For this we sought to identify the different spliceoforms of the apoptosis regulator Bcl-2 (UniProt ID: Q07817), which are potential biomarkers for cancer and are likely to produce different fingerprints." (PMID 34729466, 2021). "The NF-κB signaling pathway plays a critical role in the survival of cancer cells and is widely known for regulating the expression of Bcl-2 proteins." (PMID 34449548, 2021).
cancer (continued). "Studies have indicated that activating the p-STAT3/bcl-2 signaling pathway suppresses apoptosis in several cancers." (PMID 34170850, 2021). "Phosphorylation of its substrate GSK-3β can inhibit the translocation of Bax and the degradation of Bcl-2, leading to apoptosis inhibition of cancer cells." (PMID 34497528, 2021). "Along with regulating cellular energy and metabolism, VDAC1 is involved in mitochondria-mediated apoptosis, participating in the release of apoptotic proteins, and interacting with the anti-apoptotic proteins, Bcl2 and Bcl-xL, and HK, overexpressed in cancers." (PMID 34671273, 2021). "Keap1 appears to restrain and destabilize Bcl-2 and decrease Bcl-2:Bax heterodimers, facilitating cancer cells apoptosis." (PMID 34641325, 2021). "miR-16 and miR-15, the first described cancer-related miRNAs, stimulate cancer development by decreasing anti-apoptotic BCL2 gene in chronic lymphocytic leukemia." (PMID 35822008, 2021). "The gene expression ratio of BAX/BCL-2 indicated the induction of mitochondrial apoptosis in two cancer cell lines (SNB-19 and MDA-MB-231)." (PMID 33807874, 2021). "Previous studies revealed that Survivin and Bcl-2 upregulation can suppress the anti-cancer drug-induced apoptosis in a series of cancers, such as ovarian, breast, and lung cancer." (PMID 33738259, 2021). "The abnormal increase in NF-κB activity leads to the activation of the Bcl-2 promoter, which ultimately leads to the acceleration of the proliferation and division of cancer cells via inhibition of apoptosis, which is an important reason for Gem resistance." (PMID 35222011, 2021). "BH3 profiling of ex vivo cancer cells is already in use to predict BCL-2 dependency in hematopoietic cancers." (PMID 34781947, 2021). "In this case, Lactobacillus EPSs were found to induce apoptosis in CRC in vitro through the increased expression of Caspase 3, Caspase 9, and BAX and decreased levels of Bcl-2, which led to a decline in cancer cell survival." (PMID 34068653, 2021). "The protein BCL-2 is involved in the regulation of cell death through interference with the apoptosis pathway and is a ‘pro-survival’ protein in many types of cancer." (PMID 33226492, 2021). "Targeting the Bcl-2 rheostat by ABT-263 not only improved the cytotoxic effect of radiotherapy on cancer cells in normoxic conditions, but particularly overcomes radioresistance of cancer cells exposed to acute or cycling hypoxia in vitro and in vivo." (PMID 34257274, 2021). "Given the importance of MYC and BCL-2 proteins in cancer, it is unsurprising that there has been considerable interest in the discovery of drugs that can target both these proteins." (PMID 33799592, 2021). "The link between the modification of BCL2’s chromatin architecture and its constitutive activation in estrogen-resistant cancer cells has been demonstrated, identifying JMJD3 and methyltransferase EZH2 as interesting therapeutic targets." (PMID 33478063, 2021). "Resistance to apoptosis in cancer can be achieved through disruption in the balance of BCL-2 proteins to enhance pro-survival functions." (PMID 33785871, 2021). "Previous studies have reported that apigenin inhibits the expression of various anti-apoptotic Bcl-2 family proteins, including Bcl-xL, Mcl-1 and Bcl-2 in several cancer cell lines." (PMID 34914725, 2021). "Both BCL1 and BCL2 are known to have oncogenic activities in various human malignancies and are key proteins in the induction of cellular proliferation and cancer progression." (PMID 34099764, 2021). "Under acidic condition, the C-S bond of BTS was destroyed and released SO2 that combined with PTT up-regulated the expression of Bax and Caspase-3 and inhibited the expression of Bcl-2, which significantly promoted the apoptosis of cancer cells." (PMID 34949202, 2021).
cancer (continued). "MCL1 (myeloid cell leukemia-1) is a widely recognized pro-survival member of the Bcl-2 (B-cell lymphoma protein 2) family and a promising target for cancer therapy." (PMID 34475520, 2021). "Identifying the important function played by Bcl-2 in cancer progression and development, and treatment made it a target related to therapy for multiple cancers." (PMID 34638779, 2021). "Saleem and his colleagues noted that the activation of Bax and restriction of Bcl-2 were effective in inducing apoptosis to defend against cancers." (PMID 34793477, 2021). "Within this context, targeting Bcl2 family attracted our interest given the evidence that inhibition of MDM2 and Bcl2 protein function synergistically induce apoptosis in cancer cells." (PMID 34970530, 2021). "It was further reported that Jab1 knockdown resulted in modulation of Bax (upregulation) and Bcl-2 (downregulation) expression, which subsequently led to cancer cell growth inhibition through apoptosis induction." (PMID 34577000, 2021). "Our data demonstrated that USP37 downregulation enhanced the inhibitory effect of adriamycin on MCF-7 and MCF-7/ADR cancer cells through the inhibition of Bcl-2/Bax signaling pathway." (PMID 33390801, 2021). "The JNK pathway also promotes cancer cell survival via autophagy involving Bcl-2, tumour immune evasion, compensatory cell proliferation, and interaction with other signaling components such as NF-κB, p38, and JunD." (PMID 34867402, 2021). "The up-regulation of an anti-apoptotic Bcl-2 after treating KKU-100 cells with 5-FU or TNJ ethanolic extracts alone was considered as a chemotherapeutic resistance response of the cancer cells." (PMID 34290264, 2021). "Anti-apoptotic proteins like Bcl-2 and Bcl-xL, are included in the Bcl-2 gene family and are believed to be involved in resistance to traditional way of treatment of cancer." (PMID 34031264, 2021). "These treatment strategies can restore the Bcl-2 mediated apoptosis towards normality, potentially eliminating cancer cells." (PMID 34638779, 2021). "Knockdown of endogenous HMGB1 with short hairpin RNA (shRNA) can inhibit the proliferation of cancer cells by reducing Bcl-2 and activating Bax." (PMID 34867338, 2021). "The overexpression of Bcl-2 is highly correlated with poor therapeutic efficacy among cancer patients." (PMID 34299604, 2021). "We demonstrate that cancer cells treated with FASNis can acquire a “primed-for-death” mitochondrial state with apoptotic hypersensitivity to BCL-2 specific BH3-mimetics." (PMID 34675185, 2021). "Mechanistically, while cancer cells can contain an abundance of pro-apoptotic Bcl-2 proteins, the amplification of anti-apoptotic Bcl-2 proteins can lead to BH3-only proteins being competitively depleted." (PMID 33925117, 2021). "Overexpression of the anti-apoptotic regulator BCL-2 gives a block in cell death program which is commonly found in cancer cells." (PMID 34316412, 2021). "By aiming at the expression of Notch, C-Met, and Bcl-2, miR-34a can increase the ability of cancer cells to self-renewal and survival." (PMID 34680441, 2021). "Cobimetinib combined with venetoclax downgrades the content of the MCL1 protein, and the BCL2:BIM and MCL1:BIM complexes are damaged and release BIM, thus causing apoptosis of cancer cells." (PMID 34976824, 2021). "Over the last decade there has been considerable interest in BCL‐2 inhibitors for the treatment of cancers." (PMID 32452017, 2021).